TSPO (translocator protein)
Diseases named in the same sentence as TSPO in open-access papers (continued):
Sharing a sentence is not in itself a finding about the gene and the disease.
dysplasia (1 paper, 2025). A usually neoplastic transformation of the cell, associated with altered architectural tissue patterns. "TSPO protein signal intensity from saliva samples of participants with dysplasia showed the highest median of signal intensity compared to other histopathological findings." (PMID 40961028, 2025). "TSPO protein signal intensity from saliva samples of participants with dysplasia showed the highest median compared with other histopathological findings (p-value = 0.0596)." (PMID 40961028, 2025). "The lesions with histopathology diagnoses of dysplasia showed the highest median values of TSPO protein signal intensity in the densitometry analysis compared to other histopathological findings, which may indicate a significant presence of TSPO in dysplasia lesions." (PMID 40961028, 2025).
emotional dysregulation (1 paper, 2025). "Moreover, in vivo imaging studies using TSPO tracers revealed reduced microglial activation in prefrontal–limbic regions of individuals with PTSD, with lower TSPO availability correlating with greater symptom severity, particularly anhedonia and emotional dysregulation." (PMID 41550935, 2025).
energy metabolism disorders (1 paper, 2021). "The mitochondrial abnormalities which are associated with energy metabolism disorders of CRF include the mitochondrial membranes integrity loss, translocator protein oxidative corruption, abnormal muscle mitochondrial morphologies, and defective aerobic metabolism, or both." (PMID 34326918, 2021).
esophageal cancer (1 paper, 2025). A primary or metastatic malignant neoplasm involving the esophagus. "In summary, TSPO is expressed at low levels in esophageal cancer, and its high expression is associated with a favorable prognosis." (PMID 40936684, 2025). "This trend was consistent across six cases, further validating the downregulated expression characteristics of TSPO in esophageal cancer tissues." (PMID 40936684, 2025). "In this study, we employed both cell and animal experiments to investigate the role of TSPO in the progression of esophageal cancer." (PMID 40936684, 2025). "To further validate the expression characteristics and functional roles of the key gene TSPO in esophageal cancer, we conducted a systematic expression analysis and functional experimental validation." (PMID 40936684, 2025). "The expression level of TSPO exhibited significant variation across multiple cancer types, particularly in esophageal cancer (ESCA) tissues, where its expression was markedly lower than in normal tissues (P < 0.0001)." (PMID 40936684, 2025). "Furthermore, in the mouse orthotopic esophageal cancer model, we observed a notable decrease in TSPO expression." (PMID 40936684, 2025). "Furthermore, we validated the changes in TSPO expression levels using a mouse model of orthotopically induced esophageal cancer." (PMID 40936684, 2025). "Finally, we identified TSPO as an independent predictor of esophageal cancer and validated its predictive capability." (PMID 40936684, 2025). "The analysis of tumor heterogeneity revealed a negative correlation between TSPO expression and the heterogeneity of various cancer tumor cells, particularly in esophageal cancer." (PMID 40936684, 2025). "The results of the colony formation assay demonstrated that TSPO overexpression significantly inhibited the colony-forming ability in KYSE30, KYSE450, and EC1 cells, indicating its inhibitory effect on the proliferation of esophageal cancer cells (all P < 0.001)." (PMID 40936684, 2025).
esophageal carcinoma in situ (1 paper, 2025). "In a mouse model of esophageal carcinoma in situ, TSPO expression was significantly lower than in normal tissues." (PMID 40936684, 2025).
esophageal tumor (1 paper, 2025). "In esophageal tumor tissues, TSPO expression significantly decreased, with most regions showing weak positive or negative staining and a notable reduction in staining intensity." (PMID 40936684, 2025).
Hepatitis (1 paper, 2015). Inflammation of the liver. "Although the pathogenic mechanism is different between the hepatitis and CCl4 models, TSPO may also be increased in the liver tissues of patients with hepatitis." (PMID 26612465, 2015).
herpes simplex encephalitis (1 paper, 2020). Herpes simplex virus encephalitis (HSE) is caused by the infection of the central nervous system by Herpes simplex virus (HSV) that could have a devastating clinical course and a potentially fatal outcome particularly with delay or lack of treatment. "A study using a rat model of herpes simplex encephalitis (HSE) suggested that 38, as an agonist of TSPO, is potentially suitable for visualizing mild neuroinflammation." (PMID 32283680, 2020).
HIV encephalitis (1 paper, 2020). "In HIV encephalitis, many TSPO-positive cells were co-stained with CD68, a macrophage-lineage marker." (PMID 31963507, 2020).
Hyperkeratosis (1 paper, 2025). Hyperkeratosis is a histopathological term defining a thickened stratum corneum and may be present in many different skin conditions, with many possible overlaps. "Dysplasia was the histopathological finding with the highest TSPO protein signal intensity, compared to epithelial hyperplasia and acanthosis-hyperkeratosis." (PMID 40961028, 2025).
hyperlipidaemia (1 paper, 2019). "The present study demonstrates that hyperinsulinaemia and hyperlipidaemia in normoglycaemic genetically obese male rodents is accompanied by increased protein expression of Cyp27A1, ADXR and TSPO, and nuclear transcription factor LXRα in pancreatic tissue." (PMID 30819824, 2019).
hypertrophy (1 paper, 2018). Hypertrophy is the increase in the volume of an organ or tissue due to the enlargement of its component cells. "In addition, TSPO-KO decreased associated HF markers, with lower levels of ventricular dilation, pulmonary congestion, ANP levels and extents of cardiac fibrosis and hypertrophy." (PMID 30385779, 2018).
hypothyroidism (1 paper, 2023). Abnormally low levels of thyroid hormone. "Our study showed that hypothyroidism led to increased depression-like behaviors in adult male Wistar rats, as well as increased microglia and TSPO expression in the hippocampus, Moreover, the expression of TSPO in the hippocampus is related to the depressive behavior of hypothyroid rats." (PMID 37259424, 2023).
Infertility (1 paper, 2024). "Some of the genes presented, such as CCSER1, GNAQ, NCOA2, SNRK, and TSPO, have been previously associated with fertility traits in livestock species or related to infertility in human patients (CEP78 and GPER1)." (PMID 38540441, 2024).
influenza (1 paper, 2023). An acute viral infection of the respiratory tract, occurring in isolated cases, in epidemics, or in pandemics; it is caused by serologically different strains of viruses (influenzaviruses) designated A, B, and C, has a 3-day incubation period, and usually lasts for 3 to 10 days. "Participants underwent two [18F]DPA-714 PET/MRI scans to assess TSPO signal, indicative of microglial activation, before and after receiving the seasonal influenza vaccination, which was used as an immune stimulant." (PMID 37990275, 2023). "The influenza vaccine was not shown to cause microglial activation, measured by TSPO signal, in this study." (PMID 37990275, 2023). "The influenza vaccine was not shown to be an effective stimulator of brain microglial activation, measured by TSPO-PET in any study group." (PMID 37990275, 2023).
interstitial lung disease (1 paper, 2017). A diverse group of lung diseases that affect the lung parenchyma. "TSPO PET imaging has been used to assess, in humans, macrophages involvement in interstitial lung diseases." (PMID 29114179, 2017).
invasive breast carcinoma (1 paper, 2013). A carcinoma that infiltrates the breast parenchyma. "We also demonstrate that increased TSPO levels promote breast cancer cell migration, suggesting that TSPO may contribute to the development of invasive breast cancer." (PMID 23967175, 2013).
ischemic heart disease (1 paper, 2015). "Here, we provide an overview of the emerging role of TSPO in ischemic heart disease." (PMID 25918579, 2015).
laryngeal carcinoma (1 paper, 2023). Carcinoma that arises from the laryngeal epithelium. "An association between worse DSS and low TSPO expression (p = 0.001) was found in tumors located in the oral cavity, and a trend (p = 0.091) was seen in laryngeal cancer." (PMID 38162485, 2023). "Our in silico results showed a clear association between lower TSPO expression and survival in laryngeal cancer, in line with the TMA findings." (PMID 38162485, 2023). "Only laryngeal cancer showed a trend (p = 0.096) towards worse DFS in low TSPO expressing tumors." (PMID 38162485, 2023). "Site-specific survival analyses revealed a significantly worse 5-year (p = 0.013) and 3-year (p = 0.004) OS and 3-year progression-free interval (p = 0.043) in patients with laryngeal cancer and low tumor TSPO expression, whereas no other site-specific associations were found." (PMID 38162485, 2023).
leukopenia (1 paper, 2022). "Increased TSPO expression in the bone marrow is thus likely to reflect a combination of inflammation and increased hematopoiesis in response to peripheral leukopenia and thrombocytopenia, which were seen in our animal model and are commonly encountered in septic patients." (PMID 36439175, 2022).
liposarcoma (1 paper, 2018). A usually painless malignant tumor that arises from adipose tissue. "For instance, a publication by Campioli and colleagues investigated the impact of MEHP on the relationship between the testicular translocator protein (TSPO) and the PPARs in a human liposarcoma cell line (SW 872)." (PMID 29472605, 2018).
liver failure (1 paper, 2024). A liver disease characterized by the liver losing or has lost all of its function. "Real-time polymerase chain reaction (PCR) results 3 h after induction in the propacetamol-induced liver failure group showed that TSPO gene expression in the liver increased approximately 10-fold compared to the control group." (PMID 38892130, 2024). "Western blotting results 3 h after induction in the propacetamol-induced liver failure group showed an approximately 4.0-fold increase in TSPO protein expression in the liver compared to the control group." (PMID 38892130, 2024). "Immunohistochemistry results 3 h after the induction of propacetamol-induced liver failure showed significantly higher TSPO protein expression in the liver failure group compared to the control group." (PMID 38892130, 2024). "We combined non-invasive PET imaging with ex vivo analyses to investigate the potential of TSPO as an early biomarker and assess the feasibility of [18F]GE180 PET as a tool for the early diagnosis and prognostic prediction of acetaminophen-induced liver failure." (PMID 38892130, 2024).
meningitis (1 paper, 2020). A disorder characterized by acute inflammation of the meninges of the brain and/or spinal cord. "The increase in [11C]PBR28 uptake suggests the overexpression of TSPO and increased microglial activation after experimental meningitis." (PMID 31901235, 2020). "Knowing the role of TSPO in redox homeostasis, it is noteworthy to evaluate oxidative stress after meningitis." (PMID 31901235, 2020). "Twenty-four hours after meningitis induction, we observed increased in vivo microglial activation in the meningitis groups by TSPO-PET imaging." (PMID 31901235, 2020). "Interestingly, the expression levels of TSPO in the meningitis group increased 10 days after infection in both the PFC (P < 0.05) and hippocampus (P < 0.01)." (PMID 31901235, 2020). "Furthermore, upregulated levels of TSPO, cytochrome c, and caspase-3 and caspase-9 were observed in the rat hippocampus 10 days after meningitis induction with a simultaneous reduction in cardiolipin levels." (PMID 31901235, 2020). "In our study, we confirmed the enhanced expression of TSPO in vivo, as well in the PFC and hippocampus of meningitis survivor rats." (PMID 31901235, 2020). "Twenty-four hours and 10 days after meningitis induction, rats were imaged with positron emission tomography (PET) using [11C]PBR28, a specific translocator protein (TSPO) radiotracer, to determine in vivo microglial activation." (PMID 31901235, 2020). "Because TSPO overexpression was also detected in reactive astrocytes, we determined GFAP protein expression, which was increased in both the 24-h and 10-day meningitis groups." (PMID 31901235, 2020). "Acute meningitis induction also elevated TSPO, cytochrome c, and caspase-3 levels with no change in caspase-9 levels." (PMID 31901235, 2020). "We observed elevated levels of hippocampal TSPO and cytochrome-c expression (P < 0.05) in the meningitis group, 24 h after meningitis induction, with no change in VDAC and ANT expression." (PMID 31901235, 2020). "Due to the lack of evidence on the TSPO-mediated mitochondrial pathway after meningitis, we also investigated the cardiolipin, cytochrome-c, and caspase levels in the experimental meningitis models." (PMID 31901235, 2020). "There was no significant change in the expression of TSPO, VDAC, and ANT at 24 h after meningitis induction, between the control and meningitis groups." (PMID 31901235, 2020).
metastatic prostate carcinoma (1 paper, 2017). A carcinoma that arises from the prostate gland and has spread to other anatomic sites. "Moreover, in the particular case of prostatic adenocarcinoma, TSPO protein expression was the highest in metastatic prostate cancer samples where increased expression also correlated with disease progression." (PMID 29318061, 2017).
neurofibroma (1 paper, 2025). An intraneural or extraneural neoplasm arising from nerve tissues and neural sheaths. "TSPO expression was analyzed in adjacent non-tumor tissues, benign neurofibromas, and malignant tissues using real-time PCR, western blotting, immunohistochemistry staining." (PMID 40842566, 2025). "Compared with adjacent non-tumor tissues and benign neurofibromas, TSPO expression was significantly lower in MPNST specimens." (PMID 40842566, 2025).
oropharyngeal cancer (1 paper, 2023). Carcinoma, predominantly squamous cell, arising from the epithelial cells of the oropharynx. "Subgroup analyses showed that low TSPO expression associated with worse survival particularly in p16-positive oropharyngeal cancer." (PMID 38162485, 2023). "TSPO is a prognostic biomarker in HNSCC to potentially guide treatment stratification especially in p16-positive oropharyngeal cancer." (PMID 38162485, 2023). "Our results provide a possible connection between TSPO and p16 in oropharyngeal cancer, which we hypothesize to be related to mitochondrial functionalities, such as oxidative phosphorylation." (PMID 38162485, 2023). "However, in oropharyngeal cancer, which is the most common site for HPV infection, survival was significantly worse in patients with p16-positive tumors and low TSPO expression." (PMID 38162485, 2023).
ovarian tumors (1 paper, 2024). "Protoporphyrin IX expression, an endogenous ligand of TSPO, has been demonstrated in aggressive ovarian tumors and has been used as a phototherapeutic target in conjunction with 2-aminolevulenic acid." (PMID 39612052, 2024).
overnutrition (1 paper, 2021). An imbalanced nutritional status resulting from excessive intake of nutrients. "Various studies that have characterized TSPO changes due to overnutrition were also synthesized, demonstrating that brain TSPO is responsive to the metabolic environment of the individual." (PMID 34343461, 2021).
pancreatic ductal adenocarcinoma (1 paper, 2021). An infiltrating adenocarcinoma that arises from the epithelial cells of the pancreas. "In 2018, Lanfranca and colleagues utilized [11C]PBR28, a PET tracer that targets TSPO, in a mouse model of pancreatic ductal adenocarcinoma(PDAC)." (PMID 33923410, 2021). "Targeting TSPO has also shown promise in tracking the accumulation and depletion of macrophages with [11C]PBR28 in a mouse model of pancreatic ductal adenocarcinoma (PDAC)." (PMID 33923410, 2021).
peripheral nerve injury (1 paper, 2023). Injury to a peripheral nerve. "Our previous studies have shown that the expression of liver X receptor (LXR) and translocator protein (18 kDa) (TSPO) was increased in the spinal dorsal horn after peripheral nerve injury and that either LXR agonists or TSPO agonists could alleviate neuropathic pain behaviors." (PMID 36880297, 2023).
pilocytic astrocytoma (1 paper, 2015). Pilocytic astrocytoma is a rare subtype of low-grade glioma of the central nervous system characterized by a well circumscribed, often cystic, brain tumor with a discrete mural nodule and long, hair-like projections that extend from the neoplastic astrocytes. "For the TMA generated from patients with pilocytic astrocytoma, immunohistochemistry (IHC) indicated a low level of TSPO expression, with 16/17 of the specimens scoring as low to moderate, and only 1/17 of the specimens exhibiting high TSPO levels." (PMID 26517124, 2015).
pneumococcal meningitis (1 paper, 2022). An acute purulent infection of the meninges and subarachnoid space caused by Streptococcus pneumoniae, most prevalent in children and adults over the age of 60. "We previously reported that after recovery, a similar outcome in a preclinical model of pneumococcal meningitis using [11C]PBR28/PET imaging, where the rats demonstrated microglia and astrocyte cells activation as well as significant TSPO uptake." (PMID 35606817, 2022).
postpartum depression (1 paper, 2018). A type of clinical depression that occurs after childbirth. "However, limited information is known about the role of TSPO in postpartum depression (PPD)." (PMID 29506545, 2018).
Primary lateral sclerosis (1 paper, 2021). "We have previously shown that with [11C]PBR28 whole-brain normalizations, we were able to detect significant increases in TSPO activation in chronic pain, primary lateral sclerosis, and ALS, with strong regional overlap between [11C]PBR28 SUVR60–90 and VT and/or VT ratio (DVR)." (PMID 32076115, 2021).
prion disease (1 paper, 2023). A transmissible disease that is caused by a protein that is able to induce abnormal folding of normal cellular proteins, leading to characteristic spongiform brain changes, which are associated with neuronal loss without an inflammatory response. "This demonstration of increased TSPO in experimental prion disease aligns with ours and others’ earlier findings using the first generation TSPO radiotracer [3H]PK11195." (PMID 37032328, 2023). "To this end, we examined the expression and distribution of TSPO in a murine model of prion disease, the ME7 mouse." (PMID 37032328, 2023). "In addition, TSPO overexpression in the ME7 mouse model of prion disease appears to be driven by a number of cell types: microglia/macrophages, astrocytes, neurons and endothelial cells." (PMID 37032328, 2023).
progressive multifocal leukoencephalopathy (1 paper, 2022). Progressive multifocal leukoencephalopathy (PML) is a neurological disorder that damages the myelin that covers and protects nerves in the white matter of the brain. "Mahler C, Schumacher A-M (2021) TSPO PET imaging of natalizumab-associated progressive multifocal leukoencephalopathy." (PMID 35913607, 2022).
psoriatic arthritis (1 paper, 2020). Joint inflammation associated with psoriasis. "Clinical TSPO-PET studies in healthy volunteers and subjects with rheumatoid and psoriatic arthritis have reported higher TSPO radioligand uptake in IJD subjects compared to healthy volunteers." (PMID 33284369, 2020).
retinal (1 paper, 2021). "For clarifying the involvement of TSPO in retinal human diseases, we used the ARPE19 cell culture model." (PMID 33924902, 2021). "For clarifying the involvement of TSPO in retinal human diseases, we used the ARPE19 human cell culture model." (PMID 33924902, 2021).